BRCA1 (BRCA1 DNA repair associated)
Diseases named in the same sentence as BRCA1 in open-access papers (continued):
Sharing a sentence is not in itself a finding about the gene and the disease.
ovarian carcinoma (continued). "BRCA1 and BRCA2 are involved in almost half of all families containing two or more ovarian cancer cases." (PMID 34207450, 2021). "In conclusion, the potency of inhibition of the PARP activity induced by ASA-A and ASA-B is notably correlated to their cytostatic effects on UWB1.289, UWB1.289 + BRCA1, OVCAR-3 and SKOV-3 human ovarian cancer cells." (PMID 34440232, 2021). "Given that any additional gene identified is likely to have lower penetrance than BRCA1 or BRCA2 e.g., in a large family with multiple breast/ovarian cancer cases (MS ≥ 40), it is unlikely that this will be the entire explanation for the pattern observed." (PMID 34439310, 2021). "Inhibitors of PARP generate synthetic lethality in BRCA1- and BRCA2-mutant breast/ovarian cancer cells." (PMID 33691794, 2021). "The prevalence of a personal or family history of ovarian cancer among women with PVs in BRIP1, RAD51C, or RAD51D was similar to that observed for women with PVs in BRCA1 or BRCA2 in this cohort." (PMID 33926482, 2021). "Considerable advancements in molecular biology and therapeutics have been made in the 25 years following the discovery of tumor suppressor genes BRCA1 and BRCA2 and their roles in the development of breast and ovarian cancer." (PMID 34070674, 2021). "BRCA1 and BRCA2 encode proteins involved in recombinational repair of damaged DNA and it has been found that mutations in other genes involved in the repair of DNA damage by homologous recombination, including e.g., RAD51C, RAD51D, BRIP1, PALB2, and CHEK2 may be associated with ovarian cancer risk." (PMID 33670479, 2021). "All tested chemical derivatives produced a similar outcome onto UWB1.289 + BRCA1, UWB1.289, SKOV-3 and OVCAR-3 human ovarian cancer cells, with the activity of the lactam steroid alkylators ASA-A and ASA-B being more profound than the alkylating agent POPA." (PMID 34440232, 2021). "BRCA1 and BRCA2 are tumor suppressor genes with pivotal roles in the development of breast and ovarian cancers." (PMID 34070674, 2021). "In a French breast–ovarian cancer family, a novel rare 161-kb deletion in the region extending from the NBR1 gene to the BRCA1 gene was identified." (PMID 34926299, 2021). "Here, we describe two cases of DH in BRCA1/BRCA2 genes and three cases of DM in the BRCA2 gene in five probands with breast and ovarian cancer and in their families." (PMID 33287145, 2020). "Current testing guidelines do not recommend population-based genetic testing for ovarian cancer, however population-based testing approaches may be effective in groups with a small number of common founder mutations such as the three BRCA1/2 variants in Ashkenazi Jews." (PMID 33086730, 2020). "Predicted absolute risks for BRCA1 carriers at the 5th and 95th PRS percentiles at age 50 years varied from 31% to 58% for breast, and from 5% to 13% for ovarian cancer." (PMID 32665703, 2020). "Similarly, there was an increase in BRCA1/2 protein expression at disease recurrence in paired ovarian carcinoma specimens, suggesting that an evaluation of protein expression may represent a more accurate and contemporary measure of HR competency than any genomic scar." (PMID 32192091, 2020). "Preclinical studies and clinical trials in breast, ovarian cancer, and other cancers have shown the PARP inhibitors efficacy in BRCA1- and BRCA2-mutant patients." (PMID 32903519, 2020). "Furthermore, three healthy BRCA1+2 mutation carriers and three carriers of unknown mutations with ovarian cancer as well as 18 carriers of unknown mutations without ovarian cancer were included." (PMID 32719921, 2020). "In breast and ovarian cancer cells, OLA1 directly bound to the amino-terminal region of BRCA1 and γ-tubulin, resulting in centrosome regulation." (PMID 32045367, 2020). "Because BRCA1 and BRCA2 account for ~25% of the familial breast and ovarian cancers, this section describes other breast and ovarian cancer predisposition genes." (PMID 32269964, 2020).
ovarian carcinoma (continued). "Some of these downstream FA genes are known as tumor suppressor genes in other monoallelic inherited cancers like breast and ovarian cancer (FANCD1 = BRCA2, FANCS = BRCA1, FANCN = PABLB2, FANCJ = BRIP1, FANCO = RAD51C)." (PMID 32397406, 2020). "Although three studies utilised data from whole-exome sequencing (WES) of BRCA1 and BRCA2-negative ovarian carcinoma patients, these analysed only a subset of candidate genes in the available data and included non-HGSOC tumour types in their case cohorts." (PMID 32242007, 2020). "Our study is the first comprehensive report of LGRs of BRCA1 and BRCA2 genes in Hungarian familial breast and ovarian cancer patients and the largest survey in the Middle and Eastern European region." (PMID 32629901, 2020). "While co-deletion of BECN1 with the well-established tumor suppressor BRCA1 occurs in the vast majority of BRCA1 deletion CNAs, BECN1 has not been directly tested as a tumor suppressor in the context of ovarian cancer." (PMID 31923184, 2020). "This study is the first report about the landscape of germline BRCA1 and BRCA2 PVs in a large cohort of patients affected by breast and ovarian cancer coming from the Central–South Italy." (PMID 32438681, 2020). "Similar models using Australian oncologists to provide BRCA1 and BRCA2 genetic testing, and Canadian surgeons to provide genetic testing in ovarian cancer patient populations have also been reported." (PMID 32028617, 2020). "There is extensive information on the roles of BRCA1 and BRCA2 as tumour suppressor genes in ovarian cancer and this review will instead describe the available information on the other FA proteins involved in HR." (PMID 36046263, 2020). "Germline pathogenic single nucleotide variations (SNVs) and small indels of the BRCA1 and BRCA2 genes are well-studied genetic changes in hereditary breast and ovarian cancers." (PMID 32629901, 2020). "This frequency was close to two multicenter studies from eastern and north China ovarian cancer patients by NGS 16.7% (13.1% in BRCA1 and 3.9% in BRCA2) and 28.4% (20.8% in BRCA1 and 7.6% in BRCA2), respectively." (PMID 30972954, 2019). "BRCA1, which is a key gene in the DNA damage repair pathway, was identified as having a positive correlation with SIRT5 expression in ovarian cancer, based on the GEPIA database." (PMID 31456942, 2019). "Taken together, our data revealed that circPLEKHM3 inactivates the AKT1 and canonical Wnt/β-catenin signaling pathways by regulating the expression of BRCA1, DNAJB6 and KLF4 in ovarian cancer cells." (PMID 31623606, 2019). "A complete clinical level analysis of BRCA1 and BRCA2 in hereditary breast/ovarian cancer includes the study of LGRs." (PMID 31741787, 2019). "In ovarian cancer cells, miR-9 bound directly to the 3’-UTR of BRCA1, downregulated BRCA1 expression and impeded DNA damage repair." (PMID 35582723, 2019). "This is the largest series evaluating germline BRCA1 and BRCA2 with comprehensive gene analysis in a Brazilian population of ovarian cancer patients." (PMID 30606148, 2019). "Therefore, maintaining BRCA1 functions may be important for inhibiting breast and ovarian cancers." (PMID 30006610, 2019). "In contrast to the frequencies reported in BRCA1, methylation of BRCA2 occurs in <1% of ovarian cancers." (PMID 31225507, 2019). "In platinum-resistant ovarian cancer the niraparib pembrolizumab combination demonstrated an ORR of 25%; this response rate is similar to that of the PARP inhibitor monotherapy in BRCA1/2-mutant patients in this setting." (PMID 31109041, 2019). "In this study we utilized only the sequencing strategy (of BRCA1 gene and exon 11 of BRCA2 gene) and families with histories of breast and/or ovarian cancer from different regions (Pacific, Caribbean, Coffee, Andean and Eastern) from Colombia." (PMID 31341521, 2019).
ovarian carcinoma (continued). "Importantly, mono-allelic mutations in certain FA genes including FANCD1 (BRCA2), FANCS (BRCA1), FANCN (PALB2), FANCM, FANCJ (BRIP1), and FANCO (RAD51C) that are believed to operate downstream in the pathway and implicated in HR are associated with sporadic breast and ovarian cancer." (PMID 30813363, 2019). "BRCA1 and BRCA2 were first discovered in 1994 and 1995, and to date are the genes that have the strongest influence with ovarian cancer incidence." (PMID 30362670, 2019). "For BRCA1 or/and BRCA2 among patients with both Breast and Ovarian cancer, the pooled prevalence was 9% (95% CI: 0–25%)." (PMID 30898109, 2019). "In the case of well annotated variants associated with high probabilities of developing aggressive and often fatal cancers, such as BRCA1 and BRCA2 and hereditary breast and ovarian cancer, clinical decisions are fairly clear." (PMID 31760949, 2019). "Previous studies have shown that next-generation sequencing analyses represent robust and efficient methods for the detection of BRCA1/2 alterations from FFPE tumor tissue, including ovarian cancer specimen." (PMID 31653094, 2019). "In ovarian cancer, aberrant methylation of CpG islands in tumor suppressor genes, including CDKN2B, BRCA1, APC, RASSF1, and CDH13, is a frequent event compared to that in the normal ovarian surface epithelium." (PMID 31615043, 2019). "The aim of this report is to describe results of BRCA1 and BRCA2 Next Generation Sequencing Analysis (NGS) analysis in 132 selected Italian patients with breast/ovarian cancer." (PMID 31336956, 2019). "We screened BRCA1 and BRCA2 genes in 132 Italian patients with early onset or family history of breast and/or ovarian cancers." (PMID 31336956, 2019). "We also calculated the mean number of family members tested for every BRCA1 and BRCA2 identified ovarian cancer patient before and after the educational campaign." (PMID 29506471, 2018). "In BRCA1- and BRCA2-positive women with prophylactic salpingo-oophorectomy, the ovaries showed occult primary ovarian cancer in 6 and 2%, respectively." (PMID 29177593, 2018). "It has been estimated that there are at least 40 proteins participating in this pathway, but it was the recognition that this included BRCA1 and BRCA2 that provided the stimulus to study this pathway in breast and ovarian cancer." (PMID 29925418, 2018). "There was also an increase in the number of carrier tests performed for each BRCA1 and BRCA2 index ovarian cancer patient." (PMID 29506471, 2018). "In order to value the epimutation of MGMT and BRCA1 in WBC from cancer-free women and newborns, we investigated the prevalence of the methylated BRCA1 and MGMT promoters in breast and ovarian cancer patients." (PMID 30049288, 2018). "The mean number of family members tested for each BRCA1 and BRCA2 positive ovarian cancer patient increased after the educational campaign from 2.54 to 3.27 (p = 0.071), and the number of family members identified as BRCA positive also increased significantly." (PMID 29506471, 2018). "Additionally, pathogenic variants in BRCA1 and BRCA2, autosomal dominant cancer risk genes, both crucial in the process of homologous recombination DNA repair, increase risks to CM and uveal melanoma (UM), as well as several other cancer types including breast and ovarian cancer)." (PMID 29641532, 2018). "What role, if any, these genetic alterations in BRCA1 and BRCA2 played in acquired chemoresistance of recurrent ovarian cancer remains to be investigated." (PMID 29797793, 2018). "Anetumab ravtansine showed additive interaction with doxorubicin in the ovarian cancer cell line OVCAR-8, characterized by BRCA1 methylation, in vitro, as indicated by combination indices (CI) between 0.8 and 1.2 in five repeated experiments." (PMID 30344925, 2018).
ovarian carcinoma (continued). "There are actually very few clinical studies on the role of BRCA1 methylation in the response to PARP inhibitors (PARPi), both in breast and ovarian cancers." (PMID 29882921, 2018). "In another study, IGF-I induced BRCA1 phosphorylation in an AKT-dependent manner in breast and ovarian cancer cell lines." (PMID 30323899, 2018). "Molecular analysis of BRCA1 (MIM# 604370) and BRCA2 (MIM #600185) genes is essential for familial breast and ovarian cancer prevention and treatment." (PMID 30263092, 2018). "We therefore knocked down PIN1 in BRCA2 null mammary epithelial cells and in a panel of BRCA1 and BRCA2 null ovarian cancer cells." (PMID 30590041, 2018). "Based on their family histories of breast and ovarian cancer, 12% (n = 369) of these women met USPSTF guidelines for BRCA1/2 genetic testing." (PMID 30103738, 2018). "Current methods to identify BRCA1/2 variant carriers may not be sufficient as a screening tool; population genomic screening for hereditary breast and ovarian cancer may better identify patients at high risk and provide an intervention opportunity to reduce mortality and morbidity." (PMID 30646163, 2018). "There was also an increase in the number of carrier tests performed for each positive BRCA1 and BRCA2 ovarian cancer patient." (PMID 29506471, 2018). "Together, BRCA1 and BRCA2 account for about 20 to 25% of cases of hereditary breast cancer and 15% of cases of ovarian cancer." (PMID 28651617, 2017). "There is evidence that genetic testing soon after ovarian cancer diagnosis does not add to the negative psychological response caused by the cancer diagnosis itself, but that finding out about BRCA1/BRCA2 carrier status may lead to a slight increase in the psychological burden at that time." (PMID 28780755, 2017). "There is a significant effort to create small molecular inhibitors of RAD52 in order to clinically treat BRCA1 and BRCA2 mutant breast and ovarian cancers." (PMID 29145865, 2017). "BRCA1-IRIS inhibition using a novel inhibitory peptide sensitized triple negative breast cancer cells to paclitaxel treatment and ovarian cancer cells to cisplatin treatment, in vitro and in vivo." (PMID 28499366, 2017). "BARD1 protein is encoded by sequences on chromosome 2q35 and forms a functional heterodimer with BRCA1 through the binding of their RING-finger domains which functions as tumor-suppressor in breast and ovarian cancer." (PMID 29292755, 2017). "However, the success of niraparib in significantly extending the duration of progression-free survival in all platinum-sensitive recurrent ovarian cancer patienrs, (those with and without BRCA1/2 mutations) indicates a great expansion of the population who can benefit from PARP inhibitors." (PMID 28250960, 2017). "In our center, genetic testing of BRCA1 and BRCA2 is automatically offered to every woman with epithelial ovarian cancer diagnosed below age 70 years." (PMID 28780755, 2017). "BRCA1-IRIS overexpression also correlates with increased drug resistance in breast and ovarian cancer cells." (PMID 28499366, 2017). "Primary treatment failure (platinum-based chemotherapy) in ovarian cancer was attributed to CCNE1 amplification and partly to an intact BRCA1/2 pathway." (PMID 27582547, 2017). "For ovarian cancer, the OC-PRS had a c of 0.58 (95% CI = 0.56 to 0.60) for BRCA1 carriers and a c of 0.63 (95% CI = 0.60 to 0.67) for BRCA2 carriers." (PMID 28376175, 2017). "RNF126 was found to positively regulate BRCA1 by directly interacting with E2F1 for homologous recombination in breast and ovarian cancer." (PMID 29052520, 2017).
ovarian carcinoma (continued). "New findings that RAD52 is essential for cell viability in BRCA1-, PALB2- and BRCA2- and RAD51 paralog-deficient cells, but not in normal cells, suggested that RAD52 may represent an attractive therapeutic target for killing hereditary breast cancer and ovarian cancer cells." (PMID 27649245, 2016). "In this study, we screened the entire coding regions and exon-intron boundaries of the BRCA1 and BRCA2 genes in 133 familial breast/ovarian cancer patients from eastern China." (PMID 26852015, 2016). "Of note, the three responsive ovarian cancer cell lines (SKOV3, HEYA8 and IGROV1) exhibited markedly decreased BRCA1/2 expression at both mRNA and protein levels upon BKM120 or BKM120/Olaparib treatment." (PMID 26909613, 2016). "We have also found that knockdown of endogenous Ubc9 using siRNA resulted in suppression of cell proliferation and migration of Brca1 mutant TNBC and ovarian cancer cells." (PMID 28164176, 2016). "Cells lacking the major hereditary breast/ovarian cancer predisposition genes, BRCA1 or BRCA2, or certain other HR-defective cells, reveal a bias in favor of long tract gene conversion, suggesting that this aberrant HR outcome might be connected with genomic instability." (PMID 27832076, 2016). "Furthermore, knowledge of germline BRCA1/2 status in women living with ovarian cancer directly impacts first-degree relatives (FDRs), who have a 50% probability of carrying the same mutation and are yet to be diagnosed, and therefore, could also benefit from risk-reducing prevention strategies." (PMID 27242959, 2016). "Whilst PARP inhibitors have shown clinical utility in BRCA1/BRCA2 mutant breast and ovarian cancers, the story is much less clear in the majority of TNBCs, where surrogate markers of BRCA1 deficiency have not yet been identified." (PMID 27487152, 2016). "In this study, therefore, we performed next-generation sequencing (NGS) analysis of the entire coding regions of BRCA1 and BRCA2 in 135 breast and/or ovarian cancer patients." (PMID 25802882, 2015). "The findings from this study further define the spectrum and frequency of germline BRCA1/BRCA2 mutations in women with ovarian cancer not selected for family history of cancer and could further inform the development of mutation-screening policies for French Canadians in Quebec." (PMID 25884701, 2015). "It is also well established that mutation carriers are significantly enriched in those women with ovarian cancer who also have a strong family history of breast and/or ovarian cancer, although a cancer family history is not a reliable method for identifying women with BRCA1/BRCA2 mutations." (PMID 25884701, 2015). "In this study, we determined the sequence of BRCA1 and BRCA2 in 135 breast and/or ovarian cancer patients by NGS, which was then validated using Sanger sequencing." (PMID 25802882, 2015). "Genetic testing for BRCA1 and BRCA2 provides valuable information for determining the clinical management of patients with breast/ovarian cancer." (PMID 25683334, 2015). "Among the molecular markers, HER2, KRAS, BRCA1, BRAF, and EGFR were independent and statistically significant prognostic factors for ovarian cancer patient outcomes." (PMID 26490766, 2015). "Stable knockdown cell pools of the human ovarian cancer cell lines Ovca429 and Ovca433 expressing shRNA hairpins directed against Renilla luciferase, INPP4B, PTEN and BRCA1 were generated." (PMID 25868852, 2015). "Large rearrangements in BRCA1 and BRCA2 occur in a small percentage (<1%) of patients tested for hereditary breast and ovarian cancer." (PMID 25632310, 2015). "Although genetic testing for BRCA1 and BRCA2 for women with ovarian cancer is available in the neighbouring province of Ontario, referrals for genetic testing of ovarian cancer patients is on an ad hoc basis in Quebec." (PMID 25884701, 2015).